TNF (tumor necrosis factor)
Diseases named in the same sentence as TNF in open-access papers (continued):
Sharing a sentence is not in itself a finding about the gene and the disease.
rheumatoid arthritis (continued). "TNF-α antagonist therapy (treatment with TNF-α-specific antibody: Infliximab) increased Treg cell function in patients with rheumatoid arthritis." (PMID 31681337, 2019). "During rheumatoid arthritis, neutrophils accumulate and destroy the synovial tissue in response to TNF-α and IL-6." (PMID 31362372, 2019). "Consistent with our conclusions, TNFα plays crucial roles not only in human autoinflammatory diseases but also in autoimmune diseases such as rheumatoid arthritis, psoriasis, and Crohn’s disease." (PMID 31462647, 2019). "The decreased binding of LRRFIP1/GCF2 to TNF-α promotor is likely to cause over-expression of TNF-α and various autoimmune diseases, such as rheumatoid arthritis." (PMID 30709060, 2019). "TNF-α inhibitors have been tested in many connective tissue diseases and have been shown to be effective in rheumatoid arthritis and ankylosing spondylitis, but few data are available in RP." (PMID 31689839, 2019). "The activation of TNF signaling pathway is related to a wide range of human diseases, including septicemia, diabetes, cancer, osteoporosis, multiple sclerosis, rheumatoid arthritis, and inflammatory bowel disease." (PMID 30911319, 2019). "Blood in the joint creates an inflammatory cytokine environment with many mediators, such as tumor necrosis factor alpha (TNFα), interleukin (IL)-1, matrix metalloproteinases, and others, that are also implicated in the pathology of rheumatoid arthritis (RA) and osteoarthritis." (PMID 31892201, 2019). "Since the introduction of biological therapies almost 2 decades ago, specifically, the anti-TNFα agents, major alterations of the natural history of rheumatoid arthritis (RA) and inflammatory bowel disease (IBD) have been observed." (PMID 31824506, 2019). "Overexpression of TNF-α is considered to contribute to various diseases, such as inflammatory bowel disease, rheumatoid arthritis, and sepsis." (PMID 31652851, 2019). "Agents that target the TNFα upregulation seen in these diseases have shown promising results while in the case of Crohn’s disease and rheumatoid arthritis they have become the most widely used of the biological therapies currently prescribed." (PMID 31076648, 2019). "TNF-α is a critical mediator of the autoimmune process, playing a key role in several inflammatory diseases ranging from rheumatoid arthritis, inflammatory bowel diseases, psoriasis, and uveitis." (PMID 30967865, 2019). "TNF-blocking strategies are effective for the treatment of rheumatoid arthritis however the inflammatory effect of the TNF-alpha is mediated by the receptor 1 (TNFR1) while the TNFR2 has been shown to induce immune modulation and tissue regeneration." (PMID 30804926, 2019). "The pro-inflammatory cytokine, TNF-α, which plays a major role in the development and persistence of diseases such as Crohn’s disease, psoriasis, psoriatic arthritis, and rheumatoid arthritis, is the basis for the use of anti-TNF-α therapies." (PMID 31089365, 2019). "Currently, TNF-sequestering antibodies or soluble TNF receptors are indicated for the treatment of rheumatoid arthritis and Crohn’s disease." (PMID 31847895, 2019). "In adults with rheumatoid arthritis, several studies have shown that anti-TNF therapy increases insulin sensitivity." (PMID 31331342, 2019). "There are currently successful applications in the treatment of chronic inflammatory diseases such as rheumatoid arthritis using TNFα blockers." (PMID 30818829, 2019). "TNF-α −308A allele has been reported to increase the risk of many diseases, such as cerebral malaria, systemic lupus erythematosus (SLE), rheumatoid arthritis (RA), ankylosing spondylitis, Crohn’s disease, cancer, and coronary heart disease (CHD)." (PMID 31652851, 2019). "Gold compounds decrease the expression of inflammatory cytokines (IL-1, IL-6 and TNF) in rheumatoid arthritis patients." (PMID 31308463, 2019).
rheumatoid arthritis (continued). "Anti-TNF agents have been in the first line of treatment of various inflammatory diseases such as Rheumatoid Arthritis and Crohn’s Disease, with a number of different biologics being currently in use." (PMID 31071076, 2019). "Dendritic cells that are present in the synovial fluid increase the release of TNF, IL-1β, IL-6, and IL-23 and stimulate Th17-cell differentiation, and thus IL-17 production in rheumatoid arthritis joints." (PMID 31295952, 2019). "Drug survival on ETA and on ADA decreased over time, paralleling the increasing number of available anti-TNF treatment options, corroborating findings in rheumatoid arthritis." (PMID 31145730, 2019). "Inflammatory diseases (e.g., sepsis and rheumatoid arthritis) are often characterized by excessive production of TNFα." (PMID 30897777, 2019). "These cultures spontaneously release cytokines and matrix metalloproteases without the need for exogenous stimulation and were used in the initial studies that identified anti-TNF as a potential therapeutic agent for rheumatoid arthritis." (PMID 31244825, 2019). "In particular, anti-tumor necrosis factor (TNF)-α antibody therapy has seen wide use for rheumatoid arthritis (RA), psoriasis, ankylosing spondylitis, and inflammatory bowel disease." (PMID 31620105, 2019). "Tumor Necrosis Factor-α (TNF-α) or IL-6 inhibition evidenced greater impact on rheumatoid arthritis." (PMID 30922303, 2019). "Primary lack of response and secondary loss of response (LOR) are major obstacles to the use of anti–tumor necrosis factor (TNF)-based therapies in patients with rheumatoid arthritis or inflammatory bowel disease." (PMID 31824506, 2019). "For example, some participants were prescribed a tumor necrosis factor inhibitor for rheumatoid arthritis, whereas others received cyclosporine for a solid organ transplant." (PMID 31145717, 2019). "For example, the transfection of miR-451 mimics decreases the levels of TNF-α, IL-1β, and IL-6 in synovial fibroblasts isolated from rheumatoid arthritis patients." (PMID 31652441, 2019). "Elevated levels of TNF have been found in patients with other rheumatic diseases [i.e., rheumatoid arthritis (RA)], making it a prime target for treatment." (PMID 30774631, 2019). "Intra-articular administration of tumor necrosis factor α (TNFα) inhibitor has been shown effective for the treatment of rheumatoid arthritis with potential less systemic adverse effects of anti-TNFα." (PMID 31892201, 2019). "Tumour necrosis factor (TNF) is a key cytokine during inflammatory responses and its dysregulation is detrimental in many inflammatory diseases, such as rheumatoid arthritis and inflammatory bowel disease." (PMID 30655563, 2019). "Enhanced lymphocyte infiltrations in rheumatoid arthritis synovial fluid and murine intestine are believed to correlate with increased expression of TNF-related activation-induced cytokine by LTi-like cells." (PMID 31921189, 2019). "Many cytokine inhibitors, including those targeting IL‐1β, IL‐6, and TNF‐α, have been approved for the treatment of inflammatory diseases, such as bone destruction and rheumatoid arthritis." (PMID 30414292, 2019). "The involvement of TNF-α has been identified in the pathogenesis of rheumatoid arthritis, and the blockade of TNF-α has proven to be an effective treatment for patients with rheumatoid arthritis and Crohn’s disease." (PMID 31767905, 2019). "Tumor necrosis factor inhibitor therapy for rheumatoid arthritis (RA) patients reduces disease activity and improves function." (PMID 30956738, 2019). "It has been reported that inflammatory cytokines such as IL-1β, IL-6 and TNF-α express in rheumatoid arthritis (RA) and induces osteoclastogenesis via increasing the expression of RANKL." (PMID 31763378, 2019). "For instance, the expression levels of several serum miRNAs predicted responses to TNFα inhibitors (miR-99a and miR-143 for adalimumab; miR-23a and miR-197 for etanercept) in rheumatoid arthritis." (PMID 31483849, 2019).
rheumatoid arthritis (continued). "Although hardly considered in clinical periodontitis studies, anti-inflammatory agents such as anti-TNF-α infliximab, used in for instance rheumatoid arthritis, were shown to have a stabilizing effect on the periodontal status of patients." (PMID 30924022, 2019). "Ozoralizumab, produced by Ablynx company for rheumatoid arthritis, is anti-TNF-α single domain antibody which has successfully passed phase IIa clinical trial study." (PMID 31531059, 2019). "A pivotal effect of lymphatic vessel (LV) function in joint homeostasis was identified in the tumor necrosis factor-transgenic (TNF-Tg) mouse model of rheumatoid arthritis (RA)." (PMID 31727153, 2019). "A number of anti-TNF drugs are being used in the treatment of inflammatory autoimmune diseases, such as Rheumatoid Arthritis and Crohn’s Disease." (PMID 31071076, 2019). "Another gene in the same locus as CTNNAL1 is KLF4, which has been found to interact with TNF-α in rheumatoid arthritis." (PMID 31031798, 2019). "Rheumatoid arthritis (RA) is a progressive and debilitating disease characterized by an inflammatory pannus whose growth is stimulated by TNF and IL-6." (PMID 32232095, 2019). "The TNF blockade therapy is currently a well-established treatment option for a variety of autoimmune diseases such as rheumatoid arthritis (RA), psoriasis or Crohn's disease, given the proinflammatory role of TNF in the course of these diseases." (PMID 31309173, 2019). "In clinical settings, administration of TNF inhibitors can trigger the development of autoantibodies and even lupus manifestation (i.e., drug-induced lupus) in patients with rheumatoid arthritis and inflammatory bowel diseases." (PMID 31052273, 2019). "The aim of this study was to understand the factors that influence rheumatologists’ decisions when prescribing anti-TNF treatments for people with rheumatoid arthritis in England." (PMID 31891115, 2019). "Infliximab (IFX) is a chimeric antibody neutralizing TNFα in humans and is approved for multiple applications including ulcerative colitis, rheumatoid arthritis, Crohn’s disease, or psoriatic arthritis." (PMID 31272418, 2019). "A study from China showed that compared with placebo, anti-TNF therapy in patients with rheumatoid arthritis significantly altered the levels of regulatory T cells and suppressed effector T cells." (PMID 31048714, 2019). "TNFα inhibitors have shaped the landscape of rheumatoid arthritis (RA) therapy with high clinical efficiency." (PMID 31105703, 2019). "TLR inhibitors that act upstream of TNF are under development for the treatment of sepsis, rheumatoid arthritis, systemic lupus erythematosus, and systemic sclerosis." (PMID 30301191, 2018). "For example, more than 1,000 papers were being published each year related to tumor necrosis factor and rheumatoid arthritis; but, less than 10 papers were being published each year related to A3 adenosine receptors and rheumatoid arthritis." (PMID 29614101, 2018). "‘IL-17 signaling pathway’, ‘TNF signaling pathway’, ‘Rheumatoid arthritis’, and ‘MAPK signaling pathway’ were shown to have relations with BRCA." (PMID 29671401, 2018). "Recent clinical trials with interleukin-6 receptor monoclonal antibody tocilizumab (TCZ) and tumor necrosis factor inhibitors (TNFi) for the treatment of rheumatoid arthritis demonstrated improvements with anti-TNF-α therapy and anti-IL-6 receptor therapy." (PMID 30558178, 2018). "Despite anti-TNF therapy advancements for inflammatory diseases such as rheumatoid arthritis, the burden of diseases remains high." (PMID 29636466, 2018). "TRAF3 also limits osteoclast formation induced by TNF, which mediates inflammation and joint destruction in inflammatory diseases, including rheumatoid arthritis." (PMID 30323820, 2018). "Rheumatoid arthritis (RA) physiopathology includes synovial inflammation with proinflammatory cytokine overexpression of such as tumor necrosis factor (TNF), interleukin (IL)-1, IL-6, and IL-171." (PMID 29472591, 2018).
rheumatoid arthritis (continued). "Early studies have demonstrated that the expressions of signaling pathway proteins, such as p65 and the phosphorylations of IκBα, p38, ERK1/2, and JNK were upregulated in the human rheumatoid arthritis synovial cell line MH7A induced by TNF-α." (PMID 30096961, 2018). "The strenght of this study is one of the studies in Indonesia that assessed the correlation between TNF-α levels, FFA levels, and sVCAM-1 levels in rheumatoid arthritis patients by excluding risk factors for metabolic disorders." (PMID 30123370, 2018). "This preclinical model is considered relevant to human rheumatoid arthritis (RA) as it is dependent both on TNF-α and IL17." (PMID 29799517, 2018). "Accumulation of these structural studies can provide a basis for the improvement of therapeutic agents against TNFα for the treatment of rheumatoid arthritis and other autoimmune inflammatory diseases in which TNFα plays an important role in pathogenesis." (PMID 29518978, 2018). "TNFα, IL-17A, and IL-12/23 p40 levels in serum and synovial fluid from patients with ankylosing spondylitis (AS), rheumatoid arthritis (RA), osteoarthritis (OA), or healthy controls (HC) were measured by ELISA." (PMID 29880011, 2018). "More recently, immunomodulatory agents targeting TNF-α have been approved for the treatment of Crohn's disease, rheumatoid arthritis and juvenile chronic arthritis." (PMID 30296277, 2018). "In rheumatoid arthritis, where TNF is synthetized in extra-cardiac tissues, a high level of cytokine is also linked with cardiovascular morbidity." (PMID 29895751, 2018). "Inhibition of SHP2 has recently been shown to ameliorate the responsiveness of synovial fibroblast-like cells from patients with rheumatoid arthritis that exhibit a characteristic inflammatory and invasive phenotype to tumor necrosis factor and PDGF21,22." (PMID 30108215, 2018). "TNF-α inhibitors have also been shown to be effective and safe for the treatment of various diseases like rheumatoid arthritis, ankylosing spondylitis, juvenile idiopathic arthritis, Crohn’s Disease, sarcoidosis and also uveitis." (PMID 30290779, 2018). "The collagen-induced arthritis mouse model is known as a human rheumatoid arthritis model and is reported to exhibit mRNA increases in TNF-α, IL-1β, IL-6, and IL-18 during the progression of arthritis." (PMID 29389956, 2018). "In an in vitro co-culture system, we show that Rev-erb agonist can suppress macrophage transcript levels of select inflammatory genes (IL6, TNFα, CCL2, and MMP9), which are involved in rheumatoid arthritis and implicated in alphavirus-induced joint pathology." (PMID 30568983, 2018). "In this study, we analysed the expression level of sera circulating miRNA-5196 in rheumatoid arthritis (RA) and ankylosing spondylitis (AS) patients before and after tumor necrosis factor (TNF)-α therapy as biomarkers predicting positive treatment outcome." (PMID 29744553, 2018). "The development of tumor necrosis factor (TNF) blockade strategies for inflammatory diseases such as rheumatoid arthritis (RA) and AS was a significant treatment breakthrough." (PMID 29880011, 2018). "In the hypoxia microenvironment of rheumatoid arthritis tissue, monocytes secreted several inflammatory factors, such as IL-6, TNF-α, IL-1β and MMP-3, which contributed to the joint inflammation in RA." (PMID 29456830, 2018). "Over the last 30 years, the treatment of rheumatoid arthritis (RA) has been revolutionized with the development of biologic therapies such as anti-TNF, anti-IL-6, CTLA4-Ig and anti-CD20 agents, among others." (PMID 30886973, 2018). "TNF-α is a proinflammatory cytokine that plays a fundamental role in the pathogenesis of rheumatoid arthritis." (PMID 29670900, 2018). "Many studies have shown that TNF-α expression is associated with several diseases, including CRD, rheumatoid arthritis, pneumonia, and various forms of inflammation in birds and mammals." (PMID 29652844, 2018).
rheumatoid arthritis (continued). "KEGG pathway analysis demonstrated that these genes have functions related to the TNF signaling pathway, rheumatoid arthritis, cytokine–cytokine receptor interaction, cAMP signaling pathway, HIF-1 signaling pathway, and amphetamine addiction." (PMID 29459627, 2018). "Li and coworkers demonstrated that hesperidin decreased the production of IL-1β, IL-6, and TNF-α in a rat model of rheumatoid arthritis." (PMID 30347737, 2018). "Despite underwhelming results of anti-TNF in sepsis, the successful use in rheumatoid arthritis (RA) spurred trials in other chronic inflammatory diseases such as Crohn's disease, psoriasis and psoriatic arthritis." (PMID 30555460, 2018). "A prototypic disease with systemic sterile inflammation characterized by elevated levels of IL-1β and TNF-α is rheumatoid arthritis (RA)." (PMID 30108259, 2018). "Studies showed that TNF-α contributes to many human autoimmune diseases by promoting the expansion and survival of T cells, including diabetes, rheumatoid arthritis, and psoriasis." (PMID 29335495, 2018). "Adalimumab is a therapeutic anti-TNF mAb which is effective in the treatment of rheumatoid arthritis (RA) and other autoimmune diseases." (PMID 29632537, 2018). "Therapeutic neutralization of the inflammatory cytokines, in particular TNF, has revolutionized the treatment of autoimmune diseases including rheumatoid arthritis (RA), Crohn’s disease, spondyloarthritis (SpA), and others." (PMID 31544893, 2018). "Drugs that block the action of TNF have been shown to be beneficial in reducing the inflammation in inflammatory diseases, such as Crohn's disease and Rheumatoid Arthritis." (PMID 30713550, 2018). "The water extract of Andrographis Herba has ability to bind TNF alpha in HerboChips, and this herbal extract is being developed as a product for rheumatoid arthritis." (PMID 29681968, 2018). "Newer treatment options have been introduced for rheumatoid arthritis (RA) in the past decades and anti-tumor necrosis factor (TNF) alpha agents have been well established as the first-line biologic agent of choice." (PMID 29514712, 2018). "Volin found that in the case of rheumatoid arthritis in the synovial fluid with fibroblasts of the synovial tissue stimulated with IL-1b or TNF-α 40- to 50-fold higher R/C than in unstimulated tissue." (PMID 30174768, 2018). "Anti-TNF therapy indications include Crohn’s disease (n = 6), psoriasis and/or psoriatic arthritis (n = 8), ankylosing spondylitis (n = 8), rheumatoid arthritis (n = 1), as well as SAPHO (n = 1) and juvenile rheumatoid arthritis (n = 1)." (PMID 29295985, 2018). "Tumor necrosis factor alpha (TNF-α) expression amplifies to excess amounts in several disorders such as rheumatoid arthritis and psoriasis." (PMID 29881431, 2018). "NKG2D+ CD4+ T cells were initially found on peripheral blood and synovial fluid from rheumatoid arthritis (RA) patients, putatively as result of increased TNF-α and IL-15 levels in this disease." (PMID 29740438, 2018). "Epidemiological studies indicate that AD is less prevalent in patients on anti‐TNF blockers for rheumatoid arthritis, but clinical trials using anti‐TNF blockers in AD patients have been inconclusive." (PMID 29472246, 2018). "Of 132 DEGs, 127 were strongly enriched (Benjamini p-value < 0.05) in functions related to the TNF signaling pathway, rheumatoid arthritis, cytokine–cytokine receptor interaction, cAMP signaling pathway, HIF-1 signaling pathway, and amphetamine addiction." (PMID 29459627, 2018). "At present, etanercept, an anti-TNF drug administered in the treatment of rheumatoid arthritis, is the only TNF inhibitor (or even TNF directed treatment) tested for IAV treatment." (PMID 30042762, 2018). "In contrast, we previously observed a correlation between the reduction in aortic inflammation and reduction in aortic stiffness following anti-TNF therapy in rheumatoid arthritis patients." (PMID 29793484, 2018).